IL4 (interleukin 4)
Diseases named in the same sentence as IL4 in open-access papers (continued):
Sharing a sentence is not in itself a finding about the gene and the disease.
Hypercholesterolemia (4 papers, 2010 to 2021). An increased concentration of cholesterol in the blood. "Our observation of an increased capacity of splenocytes from mice given high-fat diet to secrete IL-4 is also in accordance with a hypercholesterolemia-dependent shift towards Th2." (PMID 21126329, 2010). "While an increase of IFN-γ was found in course of moderate hypercholesterolemia, severe hypercholesterolemia seems to be characterized by a Th2 shift, with an increase of IL-4: notably, cortisol and catecholamines, released during stress response, are involved in fat mobilization." (PMID 23204981, 2012). "However, the observation that high-fat diet increased the capacity of splenocytes to secrete IL-4 suggests that hypercholesterolemia stimulated a shift towards Th2 also in the present study." (PMID 21126329, 2010). "To further asses the effect of hypercholesterolemia on the balance between Th1 and Th2 cells we analyzed the release of IFN-γ, IL-4 and IL-10 from cultured splenocytes exposed to ConA." (PMID 21126329, 2010).
Hyperkeratosis (4 papers, 2022 to 2024). Hyperkeratosis is a histopathological term defining a thickened stratum corneum and may be present in many different skin conditions, with many possible overlaps. "IL-4/IL-13 treatment resulted in severe hyperkeratosis, spongiosis, and acanthosis in the RHE samples." (PMID 37047166, 2023). "This appears to be typical spongiosis and hyperkeratosis, in which IL-4/IL-13 cytokines suppress the maturation of desmosomes and weaken the binding of corneocytes." (PMID 35216228, 2022). "In this study, we show for the first time, that the addition of histamine to disease-associated full-thickness skin models stimulated with TH2 cytokines (IL-4, IL-13, IL-31) results in morphological changes of the epidermal layer, interpreted as hyperkeratosis." (PMID 36615633, 2023). "First, IL-4/IL-13-stimulated AD-HSE, like other in vitro AD-like models and AD patients, had altered epidermal morphology resembling spongiosis or hyperkeratosis." (PMID 35216228, 2022). "Compared with the control group, IL-4/IL-13 treatment yielded very thick EDL, even hyperkeratosis." (PMID 35216228, 2022).
hyperlipidemia (4 papers, 2022 to 2025). "Other studies supported the following: in IL-4 knockout mice, atherogenesis was inhibited despite their hyperlipidemia; the authors proposed the importance of IL-4 to be more prominent in the early phases of atherogenesis." (PMID 39944697, 2025). "However, the presence of hyperlipidemia exacerbates the inflammatory process, which may reduce the anti-inflammatory effects of IL-4." (PMID 39247699, 2024). "Unfortunately, after adjusting for hyperlipidemia, the beneficial effects of IL-4 on VaD were not significant." (PMID 39247699, 2024).
hyperplastic polyp (4 papers, 2016 to 2025). A polyp found mainly in the stomach and colon. "IL-4 promotes the development of hyperplastic polyps within the inflammatory context of collagenous gastritis." (PMID 41239618, 2025). "We found that IL-4 may be the key factor supporting the occurrence of hyperplastic polyps in collagenous gastritis." (PMID 41239618, 2025). "We conducted a STRING and PyMOL-based Protein Data Bank study and found that IL-4 may be a key factor supporting the occurrence of hyperplastic polyps in collagenous gastritis." (PMID 41239618, 2025).
hypersensitivity pneumonitis (4 papers, 2009 to 2025). Hypersensitivity pneumonitis (HP) is a pulmonary disease with symptoms of dyspnea and cough resulting from the inhalation of an antigen to which the subject has been previously sensitized. "Here, higher IL-4 levels also were detected in SSc-associated alveolitis." (PMID 19615053, 2009). "In patients with fibrotic hypersensitivity pneumonitis, ozanimod alleviated CD3/CD28 induction of CD69, IL-4, and TNF in CD8, but not CD4 T cells." (PMID 40243992, 2025).
Hypoglycemia (4 papers, 2019 to 2024). A decreased concentration of glucose in the blood. "Hypoglycemia was related to low IL-4, CXCL10, IL-6, and IFN-γ concentrations, regarding patients with normal glycemia concentrations." (PMID 36178979, 2022). "Interestingly, and unlike for the other studied cytokines, in the cytokine profile of IL-4, the highest level of IL-4 was observed in conditions imitating hypoglycemia, whereas the lowest IL-4 concentration was measured in the samples obtained from the hyperglycemic environment." (PMID 38542084, 2024). "The hitherto obtained results suggest a correlation between RSV efficacy and normal glucose concentration in MC for most analyzed cytokines, although the concentration of the only anti-inflammatory cytokine, IL-4, was the most affected by RSV in hypoglycemia conditions." (PMID 38542084, 2024).
IgG4-related disease (4 papers, 2018 to 2024). "T follicular helper cells that secrete IL-4 accumulate in lymphoid organs in IgG4-related disease and are linked to IgG4 class switching." (PMID 29984361, 2018). "Increases in cTfh2 and IL-4 are observed in IgA-vasculitis and IgG4-related disease (IgG4-RD)." (PMID 31316950, 2019). "In IgG4-related disease and Kimura disease, prominent IgG4 class switching is thought to be controlled by a population of Tfh cells co-expressing CXCR5, PD-1, ICOSL, IL-10, IL-4 and LAG-366,67." (PMID 39013889, 2024). "In contrast, in IgG4-related disease (IgG4-RD), a disorder characterized by polarized Ig class switching, most TFH cells in tertiary and SLOs make IL-4." (PMID 29984361, 2018). "In IgG4-related diseases, IL-13-positive mast cells are increased, and IgE-positive mast cells, rather than T cells, release cytokines such as IL-4 and IL-10." (PMID 35888006, 2022).
intestinal infection (4 papers, 2015 to 2023). "In addition, IL-4 has been reported to play a pathogenic role in the persistence of E. histolytica infection through the suppression of protective IFN-γ in intestinal infection." (PMID 26824828, 2016). "There is a report on the regulatory role of IL-31 interacting with its receptor in the intestine, after gastrointestinal infection by a parasite (Trichuris muris), which triggers a Th2 response and the production of IL-4 and IL-13." (PMID 35742951, 2022). "Th2 is a major source of IL-4, while IL-4 and IL-13 together coordinate alternative activation of macrophages, including upregulation of Arg-1, which may play a protective role against neurons during intestinal infections." (PMID 37138874, 2023).
intestinal tumor (4 papers, 2016 to 2025). "They found that intestinal tumor development was markedly increased in Il13−/− compared with WT mice, which further indicates a pro-tumorigenic effect of IL-4 in CRC." (PMID 27148488, 2016). "Recent research has shown that IL-4 and IL-13 promote the function of M-MDSCs and inhibit anti-tumor immunity in intestinal tumors, suggesting IL-4 and IL-13 could be potential targets for improving CRC immunotherapy." (PMID 39262952, 2024). "S9D) and treated them with either a combination of anti-IL-4 and anti-IL-13 neutralizing antibodies (αIL-4/13Ab-ILC2-SNT), or isotype control antibody (conAb-ILC2-SNT), before adding them to purified intestinal tumor M-MDSCs or splenic M-MDSCs from Apc1322T/+ mice." (PMID 35658010, 2022).
laryngeal carcinoma (4 papers, 2009 to 2024). Carcinoma that arises from the laryngeal epithelium. "This study demonstrates that compared to laryngeal cancer, IL-4, as a classic Th2 class CK, is highly expressed and has significant differences in hypopharyngeal cancer." (PMID 38920620, 2024). "This study showed differences, especially in the level of cytokines (IL-4, IL-13 and IL-10), depending on the model of direct and indirect interactions between laryngeal cancer cells and macrophages." (PMID 39057050, 2024). "The expression level of IL-4 was higher in hypopharyngeal carcinoma than in laryngeal carcinoma, and this immunosuppressive state may be related to a poorer prognosis in nasopharyngeal carcinoma." (PMID 38920620, 2024). "We assessed the serum levels of cytokines (IL–1, IL–2,IL–4, IL–6, IL–8, IL–10, IFN–gamma, TNF–alpha, GM–CSF), chemokines (MCP–1 and MIP–1alpha)and growth factors (VEGF and bFGF) in laryngeal cancer patients before, during and after surgery." (PMID 20108543, 2009).
lichen planus (4 papers, 2012 to 2025). A chronic, recurrent, pruritic inflammatory disorder of unknown etiology that affects the skin and mucus membranes. "One article examined the polymorphism of the IL-4 gene in patient with lichen planus, one article about the amount of IL-4 producing cells; one article examined the effect of IL-4 on CD 275+ cells and one article compared IL-4+ T cells levels between OLP and SCC specimen." (PMID 32134902, 2020). "It is hoped that this review article raises our awareness about the role of IL-4 in the etiopathogenesis of lichen planus and open up new ways of preventing and treating." (PMID 32134902, 2020). "Although the exact mechanism remains unclear, it has been proposed that dupilumab's inhibition of IL-4 and IL-13 may indirectly downregulate IL-6-driven Th2 responses, which are elevated in patients with lichen planus and may contribute to disease persistence." (PMID 40718341, 2025).
malignant glioma (4 papers, 2002 to 2024). A grade III or grade IV glioma arising from the central nervous system. "A Phase I trial included 31 patients with recurrent malignant glioma (25 GBM) that underwent CED infusions of IL4-PE in a dose-escalating manner.This trial showed no systemic toxicity and adverse events were mostly mild and limited to the CNS." (PMID 38261143, 2024). "Further, in malignant glioma cells, it has shown that IL-4 induces aberrant STAT3 activation, but not STAT6 activation, suggesting that a defective STAT6 signal might drive STAT3 activation." (PMID 31530290, 2019).
medulloblastoma (4 papers, 2002 to 2021). A malignant, invasive embryonal neoplasm arising from the cerebellum. "In a mouse medulloblastoma model, tumor-derived astrocytes secrete IL-4 to stimulate microglia for the production of IGF-I, which, in turn, promotes tumor growth." (PMID 34769439, 2021). "The cytotoxic activity of cpIL4-PE can be neutralized by either excess IL-4 or IL-13, indicating that IL-4R are related to IL-13R on medulloblastoma cell lines." (PMID 28752098, 2017). "Since IL-4 has been shown to modulate growth of various tumour cell lines, we examined whether it modulated growth of human medulloblastoma cell lines." (PMID 11870521, 2002). "Furthermore, a recent study of medulloblastoma models has also shown that tumor-derived astrocytes, differentiated progeny from tumor progenitors, induce polarization of resident brain microglia towards protumorigenic macrophages by secreting IL-4." (PMID 33618763, 2021). "Since, medulloblastoma cell lines did not respond to IL-4, it is reasonable to conclude that IL-4 is not a paracrine growth factor for these cells." (PMID 11870521, 2002). "The sensitivity of medulloblastoma cells to cpIL4-PE could be eliminated by concurrent incubation with IL-4 or IL-13, but not with IL-2." (PMID 11870521, 2002).
meningitis (4 papers, 2020 to 2025). A disorder characterized by acute inflammation of the meninges of the brain and/or spinal cord. "The persistent activation of microglia leads to increased inflammatory protein TNF-α and IL-4 levels, 10 days after meningitis induction." (PMID 31901235, 2020). "We also observed increased IL-4 levels (P < 0.05) and decreased IL-17 levels (P < 0.05) in the meningitis rat hippocampus, 10 days after the infection." (PMID 31901235, 2020). "Of the 13 measured, 11 (GM-CSF, IFNγ, IL-1α, IL-1Β, IL-2, IL-4, IL-6, IL-10, IL-12, IL-18, and TNF-α) exhibited higher concentrations in the saliva of pigs with meningitis and S. suis infection." (PMID 40284818, 2025). "When a panel of cytokines (including GM-CSF, IFNγ, IL-1α, IL-1β, IL-1ra, IL-2, IL-4, IL-6, IL-8, IL-10, IL-12, IL-18, and TNF-α) was measured in saliva from healthy pigs and in pigs with meningitis and S. suis infection, upregulation of several cytokines was observed in the diseased animals." (PMID 40284818, 2025).
metastatic carcinoma (4 papers, 2015 to 2023). A carcinoma which has spread from the original site of growth to another anatomic site. "This is of special importance since increased levels of IL-4 are commonly found in various types of primary and metastatic cancers, including CRC, and since IL-4 is known to act as a tumor-promoting cytokine." (PMID 38201452, 2023). "IL-4 is an important cytokine of tumor immunity, detected at high levels in several types of primary and metastatic cancers." (PMID 36324671, 2022). "Interestingly, IL-4 levels were especially enhanced in metastatic carcinoma tissues compared to those in breast duct carcinoma tissues." (PMID 27895317, 2016). "In addition, IL-4 is highly overexpressed in metastatic carcinoma tissues compared with infiltrating carcinoma tissues." (PMID 27895317, 2016).
metastatic disease (4 papers, 2016 to 2024). "IL-4 is associated with enhanced metabolic pathways in BC, thereby promoting tumor cell growth and metastatic disease." (PMID 27169467, 2016). "A tendency for an increased concentration of IL-4, IL-10 and IL-13 in blood plasma of patients with metastatic disease was evident." (PMID 39456247, 2024). "Our results also reveal that the expression of the Th2-related cytokine, IL-4, was highly upregulated in metastatic tumors compared to the other groups." (PMID 32225066, 2020). "Interestingly, metastatic tumors exhibit increased expression of CXCR3, CCR2, IL-4, IL-12p40, and IL-17." (PMID 32225066, 2020).
Newcastle disease (4 papers, 2021 to 2025). A condition caused by infection by the Newcastle disease virus, which may be characterized by conjunctivitis, respiratory illness, and diarrhea. "Newcastle disease and Infectious Bronchitis elicit immune response in chickens after intranasal administration;Inducement of higher titers of IgG and IgA antibodies;Increase the proliferation of lymphocytes and induce higher levels of cytokines, including IL-2, IL-4, and IFN-γ." (PMID 38005381, 2023). "GPS-1, Glycyrrhiza polysaccharide extract 1; ND, Newcastle disease; NDV, Newcastle disease vaccine; PHA-P, Phytin; mGM-CSF, Chicken recombinant proteins GM-CSF; il-4, Interleukin 4; chBM-DCs, immature chicken bone marrow dendritic cells." (PMID 36090181, 2022).
ocular infection (4 papers, 2010 to 2021). "In this study, we have shown that ocular infection of mice with a mixture of two avirulent HSV-1 viruses, in which one of the viruses expresses murine IL-4 increased viral pathogenesis." (PMID 21139679, 2010). "Ocular infection with parental, wild-type (WT) viruses, or with recombinant HSV-1 expressing either IFN-γ or IL-4, did not induce CNS demyelination." (PMID 28542613, 2017).
oral lichen planus (4 papers, 2012 to 2020). Oral lichen planus is a chronic inflammatory oral condition of unknown aetiology characterized by T-cell-mediated chronic immune response and abnormal epithelial keratinization cycle. "Other studies comparing salivary cytokines of clinical samples and controls found increased expression of IL-2 and IL-4 in smokers and in patients with oral lichen planus (a chronic inflammatory disease that affects the oral mucosa)." (PMID 31973090, 2020). "Background and Objectives: Interferon-gamma (IFN-γ)/interleukin-4 (IL-4) ratio may indicate a change in the immune response with a potential pathological effect presented in oral lichen planus (OLP) patients." (PMID 31181785, 2019). "A search in PubMed was performed on the literature published from 2000 until august 2019 using the following keywords: “oral lichen planus” or “OLP” and “interleukin-4” or “IL-4”." (PMID 32134902, 2020).
Peritoneal Fibrosis (4 papers, 2016 to 2024). Disorder characterized by a wide range of structural changes in PERITONEUM, resulting from fibrogenic or inflammatory processes. "IL-4-activated M2 macrophages are involved in the peritoneal fibrotic process with peritoneal M2 macrophages acting as potential targets for the interventional therapy of peritoneal fibrosis." (PMID 27082244, 2016). "In addition, the staining colocalized HDAC6 and Arginase-1 in IL-4-stimulated Raw264.7 cells, which provided support that HDAC6 might promote peritoneal fibrosis via manipulating M2 polarization." (PMID 35784347, 2022).
psoriatic arthritis (4 papers, 2010 to 2026). Joint inflammation associated with psoriasis. "Thus, inhibition of IL-4 by dupilumab may lead to enthesitis and inflammatory arthritis similar to how it occurs in spondyloarthropathy conditions such as axial spondyloarthritis and psoriatic arthritis." (PMID 39360077, 2024).
retinal degeneration (4 papers, 2020 to 2024). Degeneration of the retina. "Polymorphisms of IL-4 -590 T/T or T/C genotypes is a potential genetic marker for the development of AMD pathology, and IL-4 promotes pathological angiogenesis and choroidal neovascularization, thereby leading to retinal degeneration." (PMID 35576057, 2022). "A spontaneous retinal degeneration rd10 mouse model was also treated by IL-4 intravitreal injection." (PMID 36539414, 2022). "In conclusion, our study showed that IL-4 was decreased in retinal degeneration, and the application of exogenous IL-4 protected the RPE cells and improved neurofunction through anti-oxidative and anti-inflammatory pathways." (PMID 36539414, 2022). "The IL-4/IL-4Rα axis contributes to pathological angiogenesis through communications with bone marrow cells leading to retinal degeneration." (PMID 32366355, 2020). "Given IL-4 as the critical decreased cytokine in the degenerative retina in addition to its anti-inflammation function, we wondered whether IL-4 supplement might be protective for the retinal degeneration." (PMID 36539414, 2022). "Thus, at the context of retinal degeneration, IL-4 exhibited a new neuroprotective feature." (PMID 36539414, 2022).
RSV bronchiolitis (4 papers, 2006 to 2021). "The serum level of IL-3, IL-4, IL-10, and IL-13, which originate from Th2 cytokine, were higher in children with RSV bronchiolitis secondary wheezing, and IL-3 can be used as a predictor of recurrent wheezing." (PMID 33691633, 2021). "Each of the SNPs tested had previously been established to have a functional impact on immune responsiveness and two of the SNPs in the IL4 and IL4R genes had previously been associated with severe RSV bronchiolitis." (PMID 24949794, 2014). "The IL4 promoter and IL4R gene SNPs examined in this study have been reported to be associated with severe RSV bronchiolitis in children in Korea and the Netherlands, respectively." (PMID 24949794, 2014). "Treatment with salmeterol alone resulted in a significantly higher percentage of IL-4-producing cells characteristic of the Th2-type response observed in human infants suffering from acute RSV bronchiolitis while FPS decreased both IL-10 and IL-4." (PMID 16719922, 2006).
Sciatica (4 papers, 2019 to 2024). Pain in the lower back and hip radiating in the distribution of the sciatic nerve. "Conversely, a few anti-inflammatory molecules like IL-4 exhibited protective effects against sciatica development, further supporting the pathogenic role of inflammation." (PMID 39015317, 2024). "Previous studies have reported serum inflammatory biomarkers of sciatica, and these include TNF-α, IL-4, IL-6, IL-8, IL-10, IL-17, IL-21, T helper lymphocytes 17, phospholipase A2, C-reactive protein, C-X3-C motif ligand 1, C-C motif ligand 2 and mast cell proteinase-1." (PMID 33535986, 2021).